OR2L3 (olfactory receptor family 2 subfamily L member 3)
Description:
Odorant receptor.
Tractability: Antibody: UniProt places it where antibodies can reach, with medium confidence; UniProt predicts a signal peptide or a membrane-spanning region; its Gene Ontology location is reachable by antibodies, with medium confidence.
Gene: Protein-coding gene on chromosome 1 (248,046,836 to 248,063,407, forward strand). Ensembl gene ENSG00000198128.
Subcellular location: Cell membrane
Pathways (Reactome):
Sensory Perception: Expression and translocation of olfactory receptors
Gene Ontology:
Molecular function: olfactory receptor activity; G protein-coupled receptor activity
Biological process: detection of chemical stimulus involved in sensory perception of smell; G protein-coupled receptor signaling pathway
Cellular component: plasma membrane; membrane
Genetic constraint (gnomAD): Loss-of-function variants: 0 observed, 0.29 expected, observed/expected ratio (o/e) 0, 90% interval 0 to 1.87. That is too few expected variants to judge how well the gene tolerates losing a copy. Missense variants: 369 observed, 375.82 expected, observed/expected ratio (o/e) 0.98, 90% interval 0.9 to 1.07. Synonymous variants: 131 observed, 139.1 expected, observed/expected ratio (o/e) 0.94, 90% interval 0.82 to 1.09.
Homologues: Orthologues: chimpanzee OR2L3 (97% identical), dog OR2L3 (82% identical), dog OR2L3B (82% identical), dog OR2L5C (81% identical), dog OR2L5 (81% identical), dog OR2L17 (80% identical), mouse Or2l5 (79% identical), rat Or2l5 (79% identical). Paralogues in human: OR2L8 (96% identical), OR2L5 (88% identical), OR2L2 (85% identical), OR2L13 (71% identical), OR2AK2 (57% identical), OR2M2 (54% identical), OR2M5 (54% identical), OR2M3 (54% identical), OR2AJ1 (53% identical), OR2M7 (52% identical), OR2V2 (52% identical), OR2M4 (51% identical), and 80 more.